LEP (leptin)
Diseases named in the same sentence as LEP in open-access papers (continued):
Sharing a sentence is not in itself a finding about the gene and the disease.
Obesity (continued). "It was initially hypothesized that leptin could act as a powerful hormone to promote weight loss in adults with obesity." (PMID 40620794, 2025). "While leptin has pro-thrombotic effects, low leptin levels are paradoxically associated with an increased morbidity and mortality in patients with acute PE, a phenomenon termed the “obesity paradox”." (PMID 41226331, 2025). "Obesity is associated with high levels of leptin, and whether hyperleptinemia induces leptin resistance or not is controversial." (PMID 40650183, 2025). "Obesity may cause thrombosis due to the activity of adipocytokines, such as leptin and adiponectin, increasing coagulation activity and inflammation and decreasing the fibrinolytic cascade." (PMID 41164393, 2025). "The existence of mutations in the gene or the receptor of leptin may induce monogenic obesity; however, this event is rather scarce." (PMID 40559461, 2025). "Conversely, the development of leptin resistance—closely linked to obesity—promotes triglyceride accumulation in adipose tissue, liver, skeletal muscle, and pancreas, leading to impaired insulin secretion, decreased insulin sensitivity, and ultimately, the development of IR." (PMID 41303021, 2025). "One argument is that other adipokines (such as IL-6, TNF-α and leptin) predominate in the inflammatory profile in higher obesity states, and resistin, which is more closely linked to immune cell activation, may not scale up further with additional adiposity." (PMID 41011232, 2025). "However, leptin and insulin resistance caused by obesity result in reduced efficacy of satiety hormones like peptide YY and cholecystokinin over time, ultimately leading to decreased fullness." (PMID 40443725, 2025). "Additionally, leptin showed a positive association with patient BMI, aligning with established evidence that leptin serves as an obesity biomarker." (PMID 40880525, 2025). "Our understanding of monogenic forms of obesity largely stems from experiments in murine model systems and from case studies in humans with loss-of-function mutations that cause deficiencies of ligands or their receptors in the leptin-melanocortin pathway." (PMID 39948378, 2025). "Leptin modulates satiety through this pathway, and it has been observed in mouse models that mutations resulting in decreased leptin (synthesis, secretion, or activity) causes obesity." (PMID 41441026, 2025). "The most described adipokine, leptin, is directly implicated in obesity." (PMID 39152660, 2025). "Two single-nucleotide variants (SNVs) in the leptin gene, G19A and G2548A, located in the 5′ untranslated region (UTR) of the human leptin gene, have been reported to be associated with body mass index (BMI) and obesity, as well as leptin levels, but with discordant results." (PMID 41465332, 2025). "Our findings demonstrate significant alterations in circulating levels of FGF19, FGF21, leptin, irisin, and adiponectin, providing evidence that severe obesity is associated with dysregulated organokine networks that contribute to liver disease development and progression." (PMID 40943431, 2025). "It confirms that even normal-weight children can have cardiometabolic risk factors; and the increased WC, MAP, leptin, and insulin resistance may be associated with unhealthier conditions, including obesity." (PMID 41572970, 2025). "Although these studies have linked leptin and cytokine levels to asthma and pulmonary function in children with obesity, confirming that they aggravate the already existing asthma in such children, they cannot yet prove that asthma is a result of the inflammatory state that characterizes obesity." (PMID 41153538, 2025). "Other studies used obesity-dependent models of type 2 DM that derived from a mutation of the gene encoding leptin (ZDF rats) or its receptor (db/db mice), whose normal function precludes obesity by regulating food intake, glucose homeostasis and energy expenditure." (PMID 41446639, 2025).
Obesity (continued). "Despite this, no studies have examined whether MP-caused abnormalities in the hepatic metabolism can affect the microbial composition of the gut in leptin-deficient models with obesity phenotypes after long-term MP treatment." (PMID 41264648, 2025). "Since hyperleptinemia in obesity is associated with impaired body weight regulation, energy homeostasis, and glucose intolerance, the decrease in leptin levels may further support the metabolic benefits of myricitrin." (PMID 40286055, 2025). "Previous studies revealed that elevated leptin levels are a hallmark of obesity and indicate the development of leptin resistance, where high circulating leptin fails to suppress appetite and regulate energy balance due to impaired signaling caused by inflammation and oxidative stress." (PMID 41007669, 2025). "In leptin-deficient ob/ob mice, antioxidant supplementation rapidly reduced hyperglycemia and normalized hyperphagia, showing antioxidant therapy as a successful tool to improve glucose homeostasis in both acute and chronic models of diabetes and obesity." (PMID 41149623, 2025). "Obesity is also considered a risk factor for colorectal cancer, meaning overconsumption, type 2 diabetes and dysregulated leptin signaling could all play key roles in the development of CRC." (PMID 40289994, 2025). "Furthermore, Tsuda indicated that Cyanidin-3,5-O-diglucoside interacts with adipocytes, facilitating the secretion of lipocalin and leptin, which are significantly associated with anti-obesity effects." (PMID 40646943, 2025). "It has been suggested that obesity in humans is caused by leptin resistance." (PMID 41309900, 2025). "Although obesity is associated with hyperleptinemia, obese patients frequently develop central and peripheral leptin resistance that limits leptin's ability to be effective in target cells due to reduced ObR expression or disturbed ObR signaling." (PMID 40635334, 2025). "Indeed, mice harboring mutations in leptin (e.g., ob/ob mice) or LepRb (e.g., db/db mice) genes display severe hyperphagia, obesity, and insulin resistance." (PMID 41251447, 2025). "Moreover, it is demonstrated that low leptin levels are associated with a greater capacity for weight loss in subjects with obesity." (PMID 40650183, 2025). "This resistance results from reduced leptin transport across the blood–brain barrier and altered intracellular signaling pathways, which are frequently exacerbated by chronic inflammation associated with obesity, emphasizing leptin’s complicated function in reproductive physiology." (PMID 40002424, 2025). "While its pro-thrombotic properties are well-documented in the context of obesity, clinical data also indicate that low leptin levels may be associated with poorer outcomes in patients with acute pulmonary embolism (APE)." (PMID 41226331, 2025). "Compared with lean counterparts, obese mice (both the wild-type with HFD-induced obesity or genetically obese leptin-deficient ob/ob mice), either healthy or endotoxemic, displayed higher glycemia, cholesterolemia, alanine aminotransferase activity, liver weight, and altered liver morphology." (PMID 39861371, 2025). "Elevated maternal leptin may also alter fetal appetite regulation, increasing the offspring’s risk of obesity." (PMID 41374021, 2025). "Among the peptide hormones that influence metabolism, the correlation between leptin and antipsychotic drugs is not fully understood; hence, some studies have found that obesity and insulin resistance were commonly associated with increased serum leptin levels." (PMID 41011185, 2025). "This pathway is crucial for cellular growth and is frequently altered in tumors, indicating that leptin-induced mTOR activation may contribute to the enhanced susceptibility to CRC in individuals with obesity." (PMID 40722646, 2025). "Additionally, high levels of leptin have been associated with obesity-related conditions, including myocardial infarction and stroke." (PMID 40642747, 2025).
Obesity (continued). "Because exogenous leptin decreases feeding and body weight in lean animals, these observations led to the proposal that “leptin resistance” underlies the development and maintenance of obesity." (PMID 40393800, 2025). "Consistently, leptin-deficient Lepob/ob (ob/ob) mice and rare cases of humans with inactivating Lep mutations display hyperphagia, decreased energy expenditure, obesity, impaired glycemic control, and reduced growth and reproductive function, among other phenotypes." (PMID 40393800, 2025). "The association between obesity and poorer cognition may be affiliated to its role as a marker of vascular and inflammatory damage and that endocrine function and adipocyte leptin secretion may influence the relationship between obesity and brain health." (PMID 39976743, 2025). "Leptin deficiency or resistance can result in excessive food intake, obesity, and diabetes." (PMID 40630340, 2025). "There is still no consensus on how these two forms differ; it is generally believed that structural variations in small or large chromosomal segments lead to syndromic forms of obesity, whereas monogenic forms are caused by pathogenic variants in genes of the leptin–melanocortin pathway." (PMID 40689079, 2025). "Thus, early genetic studies of severe obesity (SevO) focused on identifying gene-disrupting mutations in the leptin-melanocortin pathway (e.g., LEPR, MC4R, POMC), which are linked to early-onset SevO through dysregulation of food intake and food preferences." (PMID 40939575, 2025). "Given that increased leptin levels are frequently linked to obesity, chronic inflammation, and insulin resistance, this reduction may have further positive cardiometabolic effects." (PMID 41157142, 2025). "Inhibition of ArcGABA neurons reduces body weight in wild-type rodents and normalizes the obesity in leptin-deficient ob/ob mice, suggesting that leptin function may be controlled by this unique set of ArcGABA neurons." (PMID 40540394, 2025). "These mice exhibited typical metabolic characteristics associated with obesity, including significant increases in body weight, adipose tissue mass, blood glucose levels, fasting serum leptin level, and fasting serum insulin level." (PMID 40160428, 2025). "Furthermore, currently we are moving toward genetic models of obesity, such as ob/ob mice (leptin-deficient) and db/db mice (leptin receptor–deficient), both of which have a C57BL/6 genetic background." (PMID 40565216, 2025). "Other research teams reported that a single-nucleotide polymorphism in FAAH (rs324420) was associated with increased obesity and may contribute to altered leptin sensitivity in humans, though there are discrepancies between the outcomes of different studies." (PMID 41096816, 2025). "Interestingly, leptin and IL-6 were the only factors associated with Cohaesibacteraceae and Rhodospirillaceae families, highlighting additional microbial signatures for obesity-enhanced psoriasis." (PMID 40869018, 2025). "Leptin gene polymorphism is also associated with MetS and obesity." (PMID 40385742, 2025). "Notably, many of these factors, together with lower ghrelin and higher leptin serum levels, are collectively associated with a dampening effect on olfactory and gustatory performance in individuals with obesity." (PMID 39970875, 2025). "Obesity has been associated to mutations in the leptin and leptin receptor genes." (PMID 40002424, 2025). "Important genes associated with monogenic obesity consist of leptin (LEP), leptin receptor (LEPR), proopiomelanocortin (POMC), prohormone convertase 1 (PCSK1), MC4R, single-minded homolog 1 (SIM1), brain-derived neurotrophic factor (BDNF), and its receptor NTRK2 (commonly referred to as TrkB)." (PMID 40428329, 2025).
Obesity (continued). "ER stress downregulates leptin expression and inhibits leptin receptor signaling, contributing to leptin resistance, increased appetite, and reduced energy expenditure.This resistance is associated with obesity-induced ER stress and the dysfunction of the mitochondria-ER interaction." (PMID 41567335, 2025). "In addition, elevated circulating leptin in obesity is associated with high blood pressure, thrombosis, and a higher risk of cardiovascular disease." (PMID 41007694, 2025). "In leptin-deficient (ob/ob) or leptin receptor–deficient (db/db) mice, PD-1 expression is reduced, and T cells retain better proliferative capacity, highlighting leptin as a driver of obesity-associated T cell exhaustion." (PMID 41432903, 2025). "For example, the leptin signaling pathway was enriched for variants in genes in 7 porcine breeds, with the highest number of genes with variants observed in the Gottingen and Meishan breeds commonly used to study obesity and metabolic syndrome." (PMID 40340757, 2025). "LEP plays a critical role in adipose tissue homeostasis, energy balance, and immune regulation, and its dysregulation has been linked to metabolic disturbances in obesity and inflammatory states, including SLE." (PMID 40292473, 2025). "Furthermore, LEP has been implicated in directly promoting cardiomyocyte hypertrophy and facilitating obesity‐related hypertension through sympathetic nervous system activation." (PMID 41143005, 2025). "The alteration of certain obesity-promoting genes (e.g., FTO and peroxisome proliferator-activated receptor gamma gene (PPARγ)) and anti-obesity genes (e.g., LEP, GLP-1R, and POMC) may be associated with obesity." (PMID 40868241, 2025). "Altered leptin levels in early life may increase the risk of overweight and obesity in offspring later in life." (PMID 40284208, 2025). "In contrast, rare case reports highlight monogenic obesity linked to leptin, LEPR, and POMC genes." (PMID 40077044, 2025). "Modulating leptin‐ and adiponectin‐related pathways may thus offer new strategies for preventing and treating obesity‐associated cancers." (PMID 41267926, 2025). "Indeed, there is an association between the circulating levels of the metabolic hormone leptin, mid-life obesity and disease risk, which has in turn stimulated interest in targeting the leptin system to treat AD." (PMID 41462981, 2025). "Key advances include CNS-targeted hesperidin delivery for leptin sensitization in obesity-associated sleep-disordered breathing, and ROS-responsive nanotherapeutics attenuating intermittent hypoxia-induced cognitive impairment through NRF2/KEAP1/HO-1 pathway modulation." (PMID 41357522, 2025). "Indeed, mutations in the gene that encodes leptin have been related to an increased frequency of obesity." (PMID 41221514, 2025). "Mouse studies have demonstrated that obesity is associated with hypothalamic resistance to leptin signaling due to leptin receptor down-regulation, and have found that the infertility associated with obesity can be rescued by exogenous gonadotropin administration." (PMID 40755647, 2025). "Indeed, the comprehensive clinical evaluations of children deficient for LEP or LEPR from consanguineous families of Pakistan have unveiled a broader health impact of these mutations beyond obesity." (PMID 39237720, 2025). "Beyond LEP and insulin, a broader spectrum of hormonal imbalances, including changes in adipokines, gut hormones, and neuroendocrine regulators, has been implicated in the systemic dysfunction characteristic of obesity." (PMID 41226484, 2025). "Hence, a lower adiponectin/leptin ratio serves as a strong indicator of oxidative stress and inflammation associated with conditions that induce major metabolic dysfunction such as obesity and metabolic syndrome." (PMID 40002337, 2025). "Additionally, short sleep duration decreases leptin levels and increases ghrelin levels, promoting obesity and thereby increasing the risk of diabetes." (PMID 41305794, 2025).
Obesity (continued). "Finally, setmelanotide can be used in older adults with monogenic obesity, caused by mutations in the leptin signalling pathway, although this is more commonly initiated in children and younger adults with severe and complex obesity." (PMID 38710803, 2025). "Only TNF-α and leptin were associated with metabolic syndrome (MetS) among the obesity group." (PMID 39837875, 2025). "Furthermore, we assessed the diagnostic utility of these adipokines, particularly leptin, in predicting obesity-related metabolic risk using receiver operating characteristic (ROC) curve analysis." (PMID 40792318, 2025). "In addition, another characteristic of diet-induced obesity is hyperleptinemia, and mutations in leptin and leptin receptors can in turn lead to obesity." (PMID 40709342, 2025). "Furthermore, the administration of GE significantly reduced the concentrations of leptin and resistin in serum, which are adipokines closely associated with obesity-related metabolic dysfunction." (PMID 41007640, 2025). "Obesity, which causes leptin resistance, further complicates interpretation." (PMID 41516046, 2025). "Mutations in leptin or its receptor (LepR) are known to cause infertility and obesity in mice." (PMID 40130278, 2025). "In obesity, the levels of leptin increase proportionally to fat mass, while its receptors’ sensibility decreases resulting in a loss of anorexigenic action, in a process called leptin-resistance." (PMID 39899119, 2025). "Studies have shown that diet-induced obesity is associated with elevated levels of inflammatory cytokines, including leptin and IL-1α, which correlate with the progression of OA, underscoring metabolic abnormalities’ role in driving inflammatory cascades that exacerbate joint pathology." (PMID 40761349, 2025). "Moreover, both leptin and IR of myocytes are associated with metabolic disorders, including obesity and the type 2 diabetes mellitus (T2DM), creating a vicious cycle augmenting muscle dysfunction." (PMID 39764565, 2025). "Leptin, a hormone secreted by adipose tissue, is increasingly recognized as a potential biomarker for assessing depression risk, particularly in the context of obesity." (PMID 40507778, 2025). "Loss-of-function mutations in LEP underlies early-onset obesity in the patient." (PMID 39041042, 2024). "It is evident that loss-of-function mutations in LEP are implicated in obesity in our research." (PMID 39041042, 2024). "Alternatively, this could be a result of catecholamine-induced inotropy linked to the effects of leptin on the sympathetic nervous system which can be seen in some phenotypes of obesity-related HF." (PMID 39477154, 2024). "Although orexin may have a bidirectional causal relationship with obesity, leptin dysregulation itself can decrease orexin levels in the brain, thereby contributing to the reduced cerebral orexin levels seen in obesity." (PMID 38553569, 2024). "A deficiency of leptin and its receptors causes severe obesity in relevant mouse models and humans." (PMID 39456156, 2024). "Obesity in pregnancy can lead to macrophage infiltration and the release of cytotoxic cytokines such as Interleukin (IL)-1β from white adipose tissue associated with increased leptin production and leptin resistance at the hypothalamus." (PMID 39377073, 2024). "However short sleep duration potentially increases obesity risk by affecting hormones, such as leptin and ghrelin, and altering dietary intake." (PMID 38542746, 2024). "Extensive previous studies have suggested that certain bioactive components in breast milk, such as leptin, adiponectin, and insulin-like growth factor-1, may play important roles in reducing the risk of offspring overweight/obesity." (PMID 38732598, 2024). "Accordingly, the finding that in obese leptin-deficient (ob/ob) and leptin receptor–deficient (db/db) mice plasma aldosterone levels are in normal range confirms the crucial role of leptin in sustaining increased aldosterone production in obesity." (PMID 38186879, 2024).